ABCA1 (ATP binding cassette subfamily A member 1)
Diseases named in the same sentence as ABCA1 in open-access papers (continued):
Sharing a sentence is not in itself a finding about the gene and the disease.
infection (continued). "Thus, ABCA1 may have a dual role, sometimes favoring infection and sometimes conferring protection." (PMID 33562440, 2021). "We identified that both ABCA1 and APOA1 genes are induced in the first 2–6 h of Mo-DC infection, and still occurs following infection with the ΔactAΔgcpE strain." (PMID 34381163, 2021). "Accordingly, the least ABCG1, ABCA1 and ACAT1 proteins in BCG-infected RAW264.7 cells were found at 12 h post infection, while the least ABCA5 and ABCA6 were at 24 h post infection." (PMID 32397995, 2020). "Of interest, the least ABCA1 and ACAT1 proteins in BCG-infected bovine AMs were observed at post infection 6 h, while the ABCG1 was at 12 h, and the least ABCA5 and ABCA6 were at 24 h post infection." (PMID 32397995, 2020). "However, another Lxr target gene, Abcg1 was upregulated more than fivefold, whilst transcription of both Srbp1c and Abca1 were comparatively unaffected by infection, suggesting that there may be redundancy in the Lxr pathway involved in regulation of these genes during Plasmodium infection." (PMID 31299982, 2019). "Our initial studies confirmed that, like other LXR target genes such as ApoE and ABCA1, AIM MФ mRNA expression was induced in response to infection." (PMID 24223991, 2013). "Transporters such as ABCA1 and APOA1 have been proposed to export IPP and ABCA1, but not APOA1 expression, is reduced in human dendritic cells when mevastatin is used during an infection with HMBPP-deficient L. monocytogenes mutants." (PMID 40667022, 2025). "Upregulation of ABCA1 and ABCG1 in APCs induces free cholesterol efflux that reduces the cell’s lipid rafts and downregulates the intra-membrane receptors required for HIV-1 trans-infection." (PMID 38140588, 2023). "To determine whether Lm induction of the ABCA1 gene and APOA1 was dependent on phosphoantigen production in the cells we blocked production with mevastatin in conjunction with infection and determined gene induction." (PMID 34381163, 2021). "Mevastatin treatment decreased transcription of ABCA1, and mevastatin limits, but does not completely prevent ABCA1 expression following infection with Lm." (PMID 34381163, 2021). "Infection with conditional shRNA AAV9 against Abca1 also did not affect the change in body temperature, indicating that Abca1 is not involved in the phenotypic changes in miR-33f/fDBH-Cre mice." (PMID 33594062, 2021). "LXRα activation in THP-1 macrophages increased the expression of the ATP-binding cassette transporters ABCA1 and ABCG1, which are responsible for lipid efflux, resulting in decreased lipid body formation during infection with attenuated M. tuberculosis strain H37Ra." (PMID 30897154, 2019). "This knockdown led to increased survival of intra-cellular M. tuberculosis and M. abscessus and this was not due to differences in infection rate in macrophages where ABCA1 was knocked down." (PMID 27462310, 2016). "No inhibition of infection was observed when the drug was added at several time points (2 h, 4 h and 6 h) after infection, suggesting that ABCA1 stimulation does not impair virus replication." (PMID 24646941, 2014). "Consistent with the requirement of ABCA1 stimulation to induce the inhibitory effect by GW3965 treatment, the drug did not decrease infection levels in ABCA1-silenced cells." (PMID 24646941, 2014). "Infection with HCV did not modify ABCA1 gene expression in Huh7.5 cells during 72 h cell growth (not shown)." (PMID 24646941, 2014). "While the observed changes in Lxrα and Abca1 expression were similar between wild-type and B6.Apoeshl mice with both short-term and long-term infections, Lxrβ gene expression was not affected by oral infection with P. gingivalis in B6.Apoeshl mice." (PMID 21625524, 2011).
infection (continued). "Furthermore, no inhibitory effect was noted when the drug was applied at different time points post-infection implying that pre-treatment of cells with the drug stimulating ABCA1 impaired virus entry, but did not affect later steps of the virus life cycle." (PMID 24646941, 2014). "Because of the importance of lipid metabolism in atherogenesis and the involvement of infection and inflammation in lipid metabolism, the gene expression levels of several cholesterol transport molecules liver X receptors (LXR) α, βand ATP-binding cassette A1 (ABCA1) were examined." (PMID 21625524, 2011).
metabolic disease (10 papers, 2008 to 2025). A congenital disorder (due to inherited enzyme abnormality) or acquired (due to failure of a metabolically important organ) disorder resulting from an abnormal metabolic process. "Regarding metabolic diseases, ABCA1 has attracted the most attention compared with that of the other ABC transporters." (PMID 32774439, 2020). "Taken together, our data suggest that ER stress in metabolic disorders reduces HDL biogenesis due to impaired hepatic ABCA1 function." (PMID 24179149, 2014). "Abca1 null mice become more glucose intolerant, whereas Scd1 and Srebp1c null mice are protected against these diet-induced metabolic disorders." (PMID 18457598, 2008). "Overall, this study provides new evidence for the important role of ABCA1 in cholesterol metabolism and metabolic diseases, suggesting that ABCA1 may have potential clinical development value." (PMID 40808841, 2025). "Among ABC transporters, ABCA1 and ABCG1 have received the most attention regarding metabolic diseases." (PMID 32774439, 2020). "Recently, the role of ABCA1 and ABCG1 in metabolic diseases has been the most studied." (PMID 32774439, 2020).
genetic disorder (9 papers, 2007 to 2025). "Two predominant genetic disorders are associated with ABCA1 mutations." (PMID 39691320, 2024). "Studies have revealed that the members of the ABCA subfamily are significantly involved in membrane lipid trafficking (ABCA1, A3, A5, and A9 are detected in almost all tissues) and in cholesterol homeostasis and they have been associated with some inherited diseases." (PMID 36557005, 2022).
kidney disease (9 papers, 2011 to 2025). "The observation that Abca1 deficient mice develop a glomerular phenotype on a high fat diet deficiency may indicate that Abca1 deficiency leads to increased susceptibility for the development of renal disease." (PMID 25352833, 2014). "Our long-term interest in the role of ABCA1 in kidney disease led us to evaluate the 5-arylnicotinimides in in vitro and in vivo models of renal disease." (PMID 34341345, 2021). "In conclusion, we show that small molecule drugs targeting OSBPL7 reveal an alternative mechanism to upregulate ABCA1, and may represent a promising new therapeutic strategy for the treatment of renal diseases and other disorders of cellular cholesterol homeostasis." (PMID 34341345, 2021). "Together, these data suggest alternative approaches to upregulate ABCA1-mediated cholesterol efflux may offer effective treatments for FSGS and other renal diseases." (PMID 34341345, 2021).
neurodegenerative disease (9 papers, 2012 to 2025). A disorder of the central nervous system characterized by gradual and progressive loss of neural tissue and neurologic function. "Neuron and glia specific ABCA1 deficiency leads to poor lipidation of apoE, and significant decrease of cholesterol level, decrease of apoE level in brain, leading to the pathological injuries that are tightly associated with degenerative diseases neurodegenerative diseases." (PMID 35296367, 2022). "Further studies are needed to better understand this process, and to decipher the role of the LXR/ABCA1 axis in HBP during neurodegenerative diseases onset and progression." (PMID 36983062, 2023). "To demonstrate the potential of this technique for understanding the pathogenesis of neurodegenerative disease, we applied our SILK technique to determine the effect of ATP binding cassette A1 (ABCA1) on both apoE and Aβ clearance." (PMID 22512932, 2012).
peripheral neuropathy (6 papers, 2015 to 2026). A disorder affecting the peripheral nervous system. "The same effect can be observed in the peripheral blood vessels, excessive cholesterol deposits due to ABCA1 dysfunction, can cause peripheral neuropathy and angiogenesis." (PMID 35069435, 2021). "Independently, studies have revealed the altered expression of ABCA1 and dysregulation of cholesterol metabolism in a host of inherited peripheral neuropathies engaging the Peripheral Myelin Protein 22 (PMP22), suggesting shared pathophysiology." (PMID 41750400, 2026). "For rs363717 (1896 A > G) in ABCA1, which was selected based on its association with thalidomide-related peripheral neuropathy, we did not observe a significant association with sensory neurotoxicity." (PMID 25881102, 2015).
neurological disorders (5 papers, 2021 to 2025). "LXR/ABCA1 axis controls cholesterol homeostasis within the CNS, and disturbances in this signaling pathway might contribute to several neurological disorders such as in AD." (PMID 36983062, 2023). "When comparing ALS with other neurological disorders (OND), ABCA1 expression in the frontal cortex showed opposite directions across datasets (GSE153960: log2FC = 1.52, p = 1.5 × 10−12; GSE124439: log2FC = −0.54, p = 0.046)." (PMID 41602910, 2025).
bacterial infection (3 papers, 2013 to 2023). "More importantly, viral or bacterial infection decreases the expression of LXRα and that of its target genes, including ABCA1." (PMID 23878415, 2013). "To investigate how bacterial infection impacts placental efflux transport potential, we investigated the expression of the of Abca1, Abcb1a, Abcb1b, Abcb4, Abcc2, Abcc5, Abcf2, Abcg1 and Abcg2 mRNAs in the mouse placenta at GD15.5 or GD18.5 following LPS challenge (4 h)." (PMID 34394055, 2021). "Release of the pro-inflammatory LPS upon bacterial infection of the wounds may induce the expression of Dnmt1, which in turn upregulates the expression of CD36 and downregulates the expression of SOAT1 and ABCA1, probably by a DNA-methylation-based mechanism." (PMID 37291182, 2023).
heart disease (3 papers, 2015 to 2025). "These highly homologous genes from the same family have been investigated in great depth, with ABCA1 being tightly linked to cholesterol levels and heart disease, therefore, suggesting a possible role for the mutated ABC transporters in CHD." (PMID 25550428, 2015). "Although the role of PPAR-γ in the development of heart disease is controversial, the activation of PPAR-γ/LXR-α-induced ABCA1 transcription supports the hypothesis that is has an effect on its development." (PMID 25601961, 2015).
inflammation (2 papers, 2020 to 2024). Aberrant reaction of the microcirculation characterized by movement of fluid and leukocytes from the blood into extravascular tissues. "Studies using murine models of experimental asthma have identified a role for the apoA-I/ABCA1 pathway in mediating neutrophilic airway inflammation; it was demonstrated that endogenous apoA-I negatively regulates ovalbumin-induced neutrophilic airway inflammation." (PMID 33271807, 2020).
lung (2 papers, 2022 to 2024). "Similar features are in part observed in knockout animals for some key LXR target genes, such as Abca1 -/- or Abcg1-/-, including the development of lung lipidosis, supporting that LXR activity is key to modulate lipid metabolism in the lung." (PMID 38970705, 2024).
hematological diseases (1 paper, 2020). "Interestingly, upon MAT2A inhibition, we detected the cholesterol efflux transporters ABCG1 and ABCA1 of the cholesterol metabolism to be significantly upregulated, resulting in known anti-proliferative and apoptotic effects in hematological diseases." (PMID 32456310, 2020).
immune disorders (1 paper, 2023). "Apart from immune disorders, the HIV-1-specific viral protein can directly block ABCA-1-mediated cholesterol efflux to HDL particles, resulting in intracellular accumulation of lipids and enhanced foam cell formation." (PMID 37705002, 2023).
peripheral nervous system disease (1 paper, 2026). "Ongoing preclinical studies in central and peripheral nervous system disease models will provide critical information on the importance of ABCA1 as a target for disease modifying intervention." (PMID 41750400, 2026).
respiratory disease (1 paper, 2020). "Notably, ABCA1 expression can be regulated via cholesterol-dependent and -independent mechanisms and the aim of the review is to explore these signaling pathways in the context of respiratory disease." (PMID 32977800, 2020).
ABCA1 also shares sentences with these, for which no sentence is quoted: cholangiocarcinoma (4 papers); gout (4); osteoporosis (3); autoimmune disease (2); cardiomyopathy (2); colorectal tumors (2); cystic fibrosis (2); Dubin-Johnson syndrome (2); fibrosis (2); Gestational Diabetes Mellitus (2); Gilbert syndrome (2); leukocytosis (2); metabolism (2); Niemann-Pick disease (2); osteoarthritis (2); Papillary Thyroid Cancer (2); Parkinson’s (2); primary open-angle glaucoma (2); Pseudoxanthoma elasticum (2); renal cell carcinoma (2); retinopathy (2); serous ovarian cancer (2); acute myeloid leukemia (1); adenocarcinoma (1); alcohol dependence (1); amyotrophic lateral sclerosis (1); aortic aneurysm (1); Aortic dissection (1); artery stenosis (1); Atrophy (1).
A further 98 diseases each share a sentence with ABCA1 in 1 paper.